CCL20 (C-C motif chemokine ligand 20)
Diseases named in the same sentence as CCL20 in open-access papers (continued):
Sharing a sentence is not in itself a finding about the gene and the disease.
infection (continued). "Group I showed greater numbers of all CCR6+ B-cell subsets and CXCR3+ naive B cells and plasma cells than did Group C. Infection of the nurslings promoted increased CCL20, CXCL10, IL-6, IL-8, total IgA, and IgG levels in the milk." (PMID 39867906, 2024). "Increased infiltration of CCR6+ lymphocytes with upregulated CCL20 expression was found in tissue microenvironment during inflammation, infection and malignant lesions in various organs, such as stomach, intestine, liver and lung." (PMID 38524129, 2024). "As comparative control, given the important role of CCL-20 in recruiting DCs and Th17 cells at the site of infection, we checked if AIEC mutants also affected CCL-20 released by intestinal epithelial HT29 cells (IECs)." (PMID 39069911, 2024). "In the milk, during infant infection, CCL20 and CXCL10 concentrations were greater in Group I than in Group C, and CXCL10 was the only chemokine that increased in the mother’s serum during infant infection." (PMID 39867906, 2024). "For example, a cytokine receptor (CSF3R) and three chemokines (CXCL8, CXCL14, CCL20) responsible for leukocyte trafficking were upregulated during infection only in birds from less-tolerant populations." (PMID 37294834, 2023). "Macrophage inflammatory proteins are also known as chemotactic cytokines that comprise CCL4 and CCL20, which play an important role in coordinating the host’s immune responses against infection." (PMID 37237892, 2023). "Compared to cells cultured with DMSO, GFs cultured in the presence of DAC released at least 10-fold higher amounts CCL20 upon infection with P. gingivalis or stimulation with TNF or IL-1β." (PMID 36776856, 2023). "In both iBEC-LMC and iBEC monocultures, CXCL8, CXCL1, CXCL2, and CCL20 were upregulated during the time course of infection, with higher upregulation of CXCL8 and CXCL1 in the monoculture model at 24 h p.i.." (PMID 36289516, 2022). "CCL20 has previously been described to have an effect on the infection steps of HIV-1 and migration/function of immune cells." (PMID 35418589, 2022). "Natural Th17cells have been also been demonstrated in the infection site using CCL20 and are further increased in the presence of IL-23." (PMID 36016187, 2022). "It was demonstrated that elevated CCL20 expression was induced in epithelial cells after infection with oral bacteria." (PMID 35408801, 2022). "To evaluate the relevance of the CCR6-CCL20 axis in the malarial immunity, we also treated WT mice with anti-CCL20 monoclonal antibodies before and during the blood-stage infection." (PMID 35730803, 2022). "The CC chemokines TARC(CCL17), PARC(CCL18) and LARC(CCL20) were measured in serum samples of AE patients and infection-free controls." (PMID 35108275, 2022). "The overexpression of CCL2 and CCL20 genes in the THP-1 monocytic cells after infection with all Aeromonas spp." (PMID 35874671, 2022). "The results show a significant upregulated mRNA expression of TNF-α, IL-1β, IL-8 and CCL20 after infection with ETEC as compared to the control condition across both groups." (PMID 36145526, 2022). "The infection of host epithelial cells suppresses the expression of the C-C motif chemokine ligand 20 (CCL20), a cytokine with anti-parasitic capacity, which is detrimental to parasite clearance." (PMID 33445463, 2021). "An increased expression of ccl20 was observed in HBMEC after infection with Salmonella tymphimurium." (PMID 34863201, 2021). "After infection with the Nm strains, ccl20 was found among the gene products most highly induced by the bacteria, even after inhibition of Erk1/2 signalling." (PMID 34863201, 2021). "PAK elicited high levels of CXCL1, CXCL5, and CCL20 in BAL fluid (BALF) at 6 hours post-infection, with lower concentrations at 24 hours." (PMID 33793661, 2021). "(F) RT-PCR analysis of IFNB1, IFIT2, IFIT1, TNF, IL6, and CCL20 mRNA levels in HEK293T cells transfected with HA-Ev or HA-RTN3 followed by infection with VSV-eGFP (MOI = 1) at the indicated timepoints." (PMID 34313226, 2021).
infection (continued). "Both CCL2 and CCL20 are myeloid chemo-attractants that alert other immune cells to the site of infection." (PMID 34943923, 2021). "Consistently, in confluent HT29 cell monolayers, LF82 triggered high levels of IL-8 and CCL20 after 7 h of infection, while either S. epidermidis or single probiotic strains induced little or no secretion of either cytokine." (PMID 32752244, 2020). "Next, we assessed the ability of probiotic strains to modulate the invasion and survival of LF82 within IECs at either 3 and 7 h after infection, as well as the induction of proinflammatory chemokines IL-8 and CCL20 at 7 h post-infection." (PMID 32752244, 2020). "Reportedly, chemokines are specialized in the recruitment of various cells, including neutrophils (IL-8), monocytes (CCL2), Th1 cells (CXCL9, CXCL10), Th2 cells (CCL17, CCL21), and Th17 cells (CCL20), to sites of infection." (PMID 32231137, 2020). "Subjects with Staph, Cor/All, Mor, and Ps/Mix clusters were found to have differences in CCL2, CCL20, IL-6, and G-CSF responses during the infection." (PMID 30061588, 2018). "The cytokines IL8, CXCL1, and CCL20 play important roles during the early phase of infection to attract different populations of immune cells and thus these were selected for measurements by ELISA." (PMID 30062089, 2018). "Chemokine expression analysis revealed that T3SS mutant induced lower mRNA levels of CXCL1, CXCL2, CXCL5, CXCL10 and CCL20 than the wild-type strain at 16 h post-infection." (PMID 30070169, 2018). "Diminished CCL20 mRNA expression following infection with T2SS and T3SS mutant strains was also observed." (PMID 30070169, 2018). "In contrast, during infection, the opposite relationship was frequently found, with IL-4, IL-13, CCL5, CCL20 and CCL24 levels associated with less severe reductions in both FVC and FEV1." (PMID 30463560, 2018). "It was shown that both hBD-2 and CCL20 were induced upon Caco-2 cell infection with EPEC, and are highly abundant in IBD patients." (PMID 30283451, 2018). "Accordingly, we found increased RNA abundance of Arg1, Socs1, Sra1, Saa1, Ciita, Marco, Mgl2, Cd209d, Cd209e, Cd209f, Ccl1, Ccl11, Ccl17, Ccl19, Ccl20, Ccl22, and Ccl24 genes in Stat2−/− mice when compared to WT mice during super-infection." (PMID 30337919, 2018). "CSF2 and CCL20 were significantly higher in cPLA2α−/− than cPLA2α+/+mice at 12 and 24 h after infection." (PMID 27501951, 2016). "Our RT-qPCR data confirmed that, upon infection with E. coli 1303, expressions of CCL20 and CXCL8 genes were induced, approx. 16 000-fold and 108-fold, respectively." (PMID 26062913, 2015). "MAPK and NF-κB signaling pathways have been shown to be involved in the CCL20 response to infections or stimulation with microbial antigens, but the contribution of each pathway varies according to the cell type and/or the pathogen considered." (PMID 26448160, 2015). "The respiratory epithelium also responds to infections with the production of several chemokines, including CCL20." (PMID 26448160, 2015). "Within 24 h of infection, expression of Il33, Tslp and Ccl20 transcripts were elevated in infected epidermis relative to naïve skin, indicating that the epidermis is a source of stimuli for APCs and T cells." (PMID 25575749, 2015). "Reduced CCL20 secretion would have a detrimental effect on the ability of keratinocytes to recruit circulating antigen presenting cells to the site of infection." (PMID 26268216, 2015). "Previous studies have shown a varying contribution of MAPK and NF-κB signaling pathways to the CCL20 response to infections or microbial antigens according to the cell type and/or the pathogen considered." (PMID 26448160, 2015). "In contrast, infection with B. abortus increased CCL20 secretion in a MOI dependent manner in both Calu-6 cells and A549 cells, although chemokine levels were much lower in the later case." (PMID 26448160, 2015).
infection (continued). "Despite the known roles of β-defensins and CCL20 in the pulmonary defense against infections, and the ability of Brucella spp." (PMID 26448160, 2015). "Naïve WT mice show similar expression of CCL2 and CCL20 as compared with naïve IL-4Rα−/− mice, and for both naïve genotypes the levels are considerably lower than upon infection with C. neoformans." (PMID 24475277, 2014). "Production of another infection-induced chemokine, Chemokine (C-C motif) ligand 20 (CCL20; also known as macrophage-inhibitory protein 3α (MIP-3α)), was also reduced by statin treatment of keratinocytes." (PMID 25010049, 2014). "Most were upregulated during infection; however, the greatest increases were in CCL20 (MIP-3α), CXCL1-3 (GROα, β and γ) and CXCL8 (IL-8)." (PMID 24436142, 2014). "The mRNA levels of IFN-gamma, IFN-alpha, IL-1, CCL20 and TNF in PBMC were variably affected by the primary Ad5hr infection, but IL-1, CCL20 and TNF were significantly decreased after subsequent Ad5 exposures." (PMID 25203111, 2014). "In vivo, recombinant CCL20 amplified the CSF pleocytosis elicited by heat-killed pneumococci 8 h after infection." (PMID 24699535, 2014). "Primary Ad5hr infection suppressed CCL20, TNF and IL-1 mRNA expression in PBMC, and subsequent virus exposures further dampened expression of these pro-inflammatory cytokines." (PMID 25203111, 2014). "The strong induction of ccl20 already after 1.5 h of infection with Giardia trophozoites is in line with our earlier results." (PMID 24228819, 2013). "It has recently been proposed that chemokine CCL20 has a role early in infection after which its levels are down-regulated by induction of IFN-γ." (PMID 23690962, 2013). "Inhibition of c-KIT with OSI930 fully restored EGR1 levels in cells infected with virulent Y. enterocolitica and significantly recovered transcription of IL-8 and CCL20 at 5 h and 20 h post-infection (dark grey bars)." (PMID 24206648, 2013). "The assessed genes were the chemokine ccl20 as positive infection control and several arginine-consuming enzymes." (PMID 24228819, 2013). "IL-17 acts on stromal cells to promote the production chemokines such as CXCL1, IL-8, CCL20 (MIP-3α) and IL-6 which then promote neutrophil recruitment to sites of infection." (PMID 23462708, 2013). "Elevated levels of CCL3, CCL4, CCL5 and CXCL9 mRNA were detected in the livers of both WT and WSX-1−/− mice on day 7 of infection, whereas CCL3, CCL4, CCL5 and CCL20 mRNA levels were increased on day 14 of infection." (PMID 24244314, 2013). "To test the role of CCR6 on Tc17 cells, we neutralized its chemokine ligand CCL20 during the effector phase (or recall response) after infection." (PMID 22829762, 2012). "The increased secretion of the chemokines CXCL1 and CCL20 is particularly important for attracting granulocytes to sites of infection." (PMID 20877575, 2010). "Human intestinal epithelial cells (IECs) secrete the chemokine CCL20 in response to infection by various enteropathogenic bacteria or exposure to bacterial flagellin." (PMID 19814810, 2009). "In gastric epithelial cells, infection with Helicobacter pylori results in the activation of the NF-kB pathway, leading to CCL20 gene transcription." (PMID 19806192, 2009). "Compared to untreated cells, infection with S. typhimurium (1 × 107 CFU/ml) or exposure to its flagellin stimulated significant secretion of CCL20 within 6 hr." (PMID 19814810, 2009). "Chemokines associated with the trafficking of DC precursors (i.e., CCL20), and mature DC, naïve T cells and central memory T cells (i.e., CCL21), do not change significantly in intestinal tissues throughout the course of infection." (PMID 19149556, 2009). "In the primary lung epithelial cells from BALB/c and C57Bl/6 mice, significant up-regulation of CCL20 was observed earlier at 0 h, 2 h and 6 h post infection (p<0.05), after which the expression level of CCL20 declined to basal level." (PMID 19806192, 2009).
infection (continued). "Dose and time response studies indicated that at a dose of 1 × 108 CFU/ml M. paratuberculosis stimulated significant secretion of CCL20 following 12 hr of infection." (PMID 19814810, 2009). "In LA-4 cells, infection with B. pseudomallei resulted in significant down-regulation of lysozyme and significant up-regulation of CCL20 and SLPI at 6 h and 24 h post infection compared to uninfected control cells (p<0.05)." (PMID 19806192, 2009). "Furthermore, the expression of TNF-α and CCL20 were notably higher following infection with P. verrucosa compared to the strains of P. submersa and P. americana (p < 0.05)." (PMID 40727705, 2025). "The cytokines and chemokines TNF-α and CCL20, which play critical roles in inflammation and immune cell recruitment, were unregulated following infection with all Phialophora species, demonstrating that these pathogens elicit an inflammatory response from the host immune system." (PMID 40727705, 2025). "Additionally, chemokine-encoding genes involved in the recruitment of immune cells such as CXCL2, CXCL3 and CCL20 were upregulated during the course of infection." (PMID 40794782, 2025). "Although the proportion of CD8+ CTLs decreased from 5.48% to 4.13% after infection, these cells exhibited enhanced expression of cytolytic genes (nkl, gzmb, gzma, and prf1) and chemokines (ccl5l, ccl20, mcp1b, and ccl4l), while decreased the expression of il34." (PMID 40821846, 2025). "However, the expression of the CCL20 gene was significantly higher after infection with the latter strain (1185C) than with the Y. enterecolitica (1186C) infection (p < 0.05)." (PMID 38721607, 2024). "In summary, CXCL6, CXCL5, and CCL20 chemokines are important for the mechanism of immune signaling during infections, playing a fundamental role in recruiting immune cells to the site of infection and enhancing the local immune response." (PMID 38474048, 2024). "Various chemokines (small proteins that guide white blood cells to sites of infection, injury, or inflammation) in this pathway, such as Cxcl1, Cxcl2, Cxcl3, and Cxcl5 and Ccl20, showed significant differences in expression levels between the LV149-L and the DSS group." (PMID 39845056, 2024). "The mRNA levels of IL-1β, IL-6, and CCL20, which are known to trigger an inflammatory response, peaked at 6 h following infection with M. gallisepticum in HD-11 cells and tracheal epithelial cells, then gradually decreased and reached the baseline 24 h post-infection." (PMID 38474071, 2024). "Additionally, the elevated expression of CCL20 across all time points following CDH1OE strain infection suggests that the Th17 immune response is more robustly activated in this context." (PMID 39728387, 2024). "Indeed, incubation of recombinant CCL20 with P. gingivalis in conditions equivalent to those used in cell infection experiments resulted in rapid degradation of the protein." (PMID 36776856, 2023). "We can therefore hypothesize that the CXCL8 and CCL20 differential responses after infection could be attributed to a differential intracellular fate of Salmonella in ileal and caecal chicken epithelial cells." (PMID 37525204, 2023). "However, CCL20 was increased significantly since 8 h of infection, and continued to increase within 24 h (*P < 0.05, **P < 0.01)." (PMID 36650424, 2023). "Consistent with SARS-CoV-2 infection of human airway epithelial cells, we observe a rapid proinflammatory response during the early stages (24 h) of infection characterized by an increased expression of multiple cytokines and chemokines (e.g., CCL20, IL-6, CXCL8 and CXCL10)." (PMID 37112842, 2023). "In fact, a previous study demonstrated a higher transcriptional level of the chemokine genes (CCL2 and CCL20) after infection of THP-1 cells with V. vulnificus, confirming that monocytes played an equally important role as other immune-related cells to control the infection process." (PMID 35874671, 2022).
infection (continued). "In addition, during infection, neutrophils secrete IL-17A that can induce the lung epithelial cells toward specific CCL20 production." (PMID 36016187, 2022). "In the absence of infection, the bioavailability of CCL20 in amniotic fluid was associated with the partum process." (PMID 36012236, 2022). "Moreover, it has been demonstrated that infection induces depletion of STAT1α and suppresses expression of CCL20 in intestinal epithelial cells, resulting in the suppression of epithelial antimicrobial defense." (PMID 33445463, 2021). "The CCR6 chemokine MIP-3α (CCL20) is produced at sites of infection in SIV animal models." (PMID 35055955, 2021). "However, an enhanced upregulation of 9 genes, all involved in the NF-kB pathway (CCL2/MCP1, CCL20, CCL4, CXCL2/MIP2α, IL1A, NFKBIA, PTX3, TNFA, TNFAIP3), was observed after infection with D26 variants, in comparison to the WT." (PMID 33399033, 2021). "Furthermore, CXCL2, CXCL,3, and CCL20 were found upregulated and identified in early infection models of SARS-CoV-2." (PMID 33602138, 2021). "RT-qPCR analysis of the expression of key components of the host innate immune response to infection, such as the chemokines/cytokines CCL20, CXCL8, TNF-α, the two β-defensins, LAP and TAP and the acute phase protein SAA3, confirmed the different abilities of R- and S-LPS to stimulate PS cells." (PMID 30142177, 2018). "Next, we found increased mRNA expression and activity levels of Arg1, mRNA expression of Fizz, Chi3l3, Cd209d, Cd209e, Mrc2 (Cd206), Marco, Il13, Saa1 (Serum amyloid A1 protein), Ccl17, Ccl19, Ccl20, Ccl22, and Ccl24 in Stat2−/− mice compared to WT mice during super-infection." (PMID 30337919, 2018). "Three out of fifteen genes that were significantly affected during the primary infection could be linked to an immune function (KLRJ1, MARCO, CCL20); one was upregulated and two downregulated." (PMID 28003017, 2016). "Because of their chemotactic and antimicrobial activities, both CCL20 and beta-defensins are postulated to have important roles in the pulmonary innate immune response to inhaled pathogens, and several studies have shown the induction of CCL20 or hBD2 in lung tissues during infection." (PMID 26448160, 2015). "As a consequence, the increased expression of CCL20 that we detected in our assays could also participate to the amplification of the host response to infection by attracting more IL-17-producing T cells to the site of infection." (PMID 26062913, 2015). "Similarly, CCL20 has been shown to be produced by lung epithelial cells and to be induced in the lungs by some infections." (PMID 26448160, 2015). "CCL20 is also produced by monocytes/macrophages in response to infections or microbial antigens." (PMID 26448160, 2015). "Collectively, these results suggest that different cell types may respond to a B. abortus pulmonary infection with the production of CCL20, potentially contributing to the recruitment of lymphocytes and dendritic cells to the infection site." (PMID 26448160, 2015). "Furthermore, the gene expression of the cytokines Cxcl9, Cxcl10, Cxcl11 and Ccl20 was increased early after infection." (PMID 25137043, 2014). "At 6 and 24 hours after infection, CCL20 levels were increased." (PMID 24699535, 2014). "Infection of AGS cells with H. pylori at various MOI resulted in CCL20 induction." (PMID 24824519, 2014). "The optimal MOI for CCL20 induction was 15, and CCL20 mRNA expression peaked at 3-h post-infection." (PMID 24824519, 2014). "A previously published study from our laboratory however, reported down-regulation of IL-12p40, IL-8, IL–1β, and CCL-20 mRNA in tracheal tissues at day-1 post-infection, whereas chemokines like MIP-1β, CXCL-13, RANTES and lymphotactin were found to be up-regulated." (PMID 25401327, 2014). "At time points later than 48 h after infection, CCL20 levels had returned to normal." (PMID 24699535, 2014).